PKN2 (protein kinase N2)
Description:
PKC-related serine/threonine-protein kinase and Rho/Rac effector protein that participates in specific signal transduction responses in the cell. Plays a role in the regulation of cell cycle progression, actin cytoskeleton assembly, cell migration, cell adhesion, tumor cell invasion and transcription activation signaling processes. Phosphorylates CTTN in hyaluronan-induced astrocytes and hence decreases CTTN ability to associate with filamentous actin. Phosphorylates HDAC5, therefore lead to impair HDAC5 import. Direct RhoA target required for the regulation of the maturation of primordial junctions into apical junction formation in bronchial epithelial cells. Required for G2/M phases of the cell cycle progression and abscission during cytokinesis in a ECT2-dependent manner. Stimulates FYN kinase activity that is required for establishment of skin cell-cell adhesion during keratinocytes differentiation. Regulates epithelial bladder cells speed and direction of movement during cell migration and tumor cell invasion. Inhibits Akt pro-survival-induced kinase activity. Mediates Rho protein-induced transcriptional activation via the c-fos serum response factor (SRF). Involved in the negative regulation of ciliogenesis. (Microbial infection) Phosphorylates HCV NS5B leading to stimulation of HCV RNA replication.
Synonyms: PRK2; PRKCL2; Pak-2; STK7; PAK2; PRO2042
Tractability: Small molecule: a structure with a bound ligand is known; a high-quality ligand is known; it belongs to a druggable protein family. Antibody: its Gene Ontology location is reachable by antibodies, with high confidence. PROTAC: ubiquitination databases record sites on it; its protein half-life has been measured; a small molecule that binds it is known.
Target class: AGC protein kinase PKN family; Enzyme; AGC protein kinase group; Protein Kinase; Kinase
Gene: Protein-coding gene on chromosome 1 (88,684,222 to 88,836,255, forward strand). Ensembl gene ENSG00000065243.
Subcellular location: Cytoplasm; Nucleus; Membrane; Cell projection, lamellipodium; Cytoplasm, cytoskeleton; Cleavage furrow; Midbody; Cell junction
Subcellular location (Human Protein Atlas): Intermediate filaments; Nucleoplasm; Centrosome; Cytosol; Nuclear bodies; Plasma membrane
Pathways (Reactome):
Signal Transduction: RAC1 GTPase cycle; RHO GTPases activate PKNs; RHOA GTPase cycle; RHOB GTPase cycle; RHOC GTPase cycle
Cellular responses to stimuli: High laminar flow shear stress activates signaling by PIEZO1 and PECAM1:CDH5:KDR in endothelial cells
Gene Ontology:
Molecular function: cadherin binding; histone deacetylase binding; kinase activity; protein binding; protein serine/threonine kinase activity; RNA binding; RNA polymerase binding; protein kinase activity; protein serine kinase activity; protein tyrosine kinase activity; ATP binding; diacylglycerol-dependent serine/threonine kinase activity; small GTPase binding
Biological process: apical junction assembly; epithelial cell migration; positive regulation of cytokinesis; positive regulation of mitotic cell cycle; positive regulation of viral genome replication; protein phosphorylation; regulation of cell motility; intracellular signal transduction; signal transduction; vascular endothelial cell response to laminar fluid shear stress
Cellular component: anchoring junction; apical junction complex; cleavage furrow; cytoplasm; intermediate filament cytoskeleton; lamellipodium; midbody; nucleoplasm; nucleus; perinuclear region of cytoplasm; protein-containing complex; cytosol; cytoskeleton; membrane
Genetic constraint (gnomAD): Loss-of-function variants: 16 observed, 56.78 expected, observed/expected ratio (o/e) 0.28, 90% interval 0.19 to 0.43. The upper end of that interval is the gene's LOEUF score, 0.43, which puts it in group 1 of 6, group 1 being the genes least tolerant of losing a copy. Missense variants: 540 observed, 742.42 expected, observed/expected ratio (o/e) 0.73, 90% interval 0.68 to 0.78. Synonymous variants: 251 observed, 248.62 expected, observed/expected ratio (o/e) 1.01, 90% interval 0.91 to 1.12.
Homologues: Orthologues: chimpanzee PKN2 (99% identical), macaque PKN2 (99% identical), guinea pig PKN2 (96% identical), dog PKN2 (96% identical), pig PKN2 (96% identical), rabbit PKN2 (96% identical), mouse Pkn2 (95% identical), rat Pkn2 (93% identical), tropical clawed frog pkn2 (85% identical), zebrafish pkn2a (76% identical), zebrafish pkn2b (76% identical), Drosophila melanogaster Pkn (55% identical), and 7 more. Paralogues in human: PKN1 (58% identical), PKN3 (47% identical), PRKCE (24% identical), PRKCG (23% identical), PRKCA (23% identical), PRKCH (23% identical), PRKCB (23% identical), PRKCI (20% identical), PRKCZ (19% identical).
Diseases named in the same sentence as PKN2 in open-access papers:
PKN2 is named in the same sentence as 58 diseases in open-access papers, as found by Europe PMC text mining. Sharing a sentence is not in itself a finding about the gene and the disease. The quoted sentences say what the papers report.
colon cancer (6 papers, 2018 to 2025). "On the contrary, PKN2 was identified to inhibit tumor-associated macrophages (TAMs) polarization and tumor growth in colon cancer." (PMID 34745257, 2021). "The expression of PKN2 in colon cancer cells predicted a favorable prognosis and was associated with low M2 macrophage content in human colon cancer tissues." (PMID 29368606, 2018). "The expression of PKN2 in colon cancer cells suppresses tumor associated M2 macrophage polarization and tumor growth." (PMID 29368606, 2018). "This study aims to investigate the effects of PKN2 on colon cancer angiogenesis under hypoxic and normoxic conditions." (PMID 40515512, 2025). "The supernatant from PKN2 knockdown colon cancer cells significantly enhanced tube formation by EA.hy926 cells." (PMID 40515512, 2025). "Our previously published work indicates that PKN2 inhibits the ERK signaling pathway in colon cancer cells." (PMID 40515512, 2025). "The effect of PKN2 on tumor angiogenesis was investigated both in cultured colon cancer cells and in a mouse colon cancer model." (PMID 40515512, 2025). "In the present study, we discovered that PKN2 expression correlated with tumor MVD in patients with colon cancer." (PMID 40515512, 2025). "RT‐qPCR was performed to assess the expression levels of proangiogenic factors by cells with PKN2 overexpression and control colon cancer cells." (PMID 40515512, 2025). "Our study demonstrated, for the first time, that PKN2 exerts inhibitory effects on tumor angiogenesis in colon cancer." (PMID 40515512, 2025). "In conclusion, our data indicated for the first time that PKN2 inhibits tumor angiogenesis in colon cancer." (PMID 40515512, 2025). "PKN2 expression was negatively correlated with tumor MVD in tumor tissue of patients with colon cancer." (PMID 40515512, 2025). "It has been demonstrated that PKN2 can influence the progression of colon cancer by regulating macrophage polarization in tumor immunity." (PMID 40069590, 2025). "In our previous study, we observed a high expression of PKN2 in colon cancer cells that inhibited tumor growth by suppressing M2‐like polarization of tumor‐associated macrophages." (PMID 40515512, 2025). "The phosphorylation of HIF‐1α was increased in colon cancer cells with high PKN2 expression, while it was decreased in cells with PKN2 knockdown." (PMID 40515512, 2025). "Our findings also indicated that PKN2‐overexpressing colon cancer cell lines were enriched in MAPK and PI3K signaling pathways, and PKN2 inhibited the phosphorylation of Erk1/2." (PMID 40515512, 2025). "We further evaluated the effects of PKN2 overexpression on the survival and body weight of mice in the subcutaneous colon cancer model." (PMID 40515512, 2025). "The coimmunoprecipitation and confocal studies showed that PKN2 directly binds to HIF‐1α in colon cancer cells." (PMID 40515512, 2025). "Our findings demonstrated a significant reduction in VEGFA and bFGF expression in PKN2‐overexpressing colon cancer cells compared to control cells, while other proangiogenic factors remained unchanged." (PMID 40515512, 2025). "At the same time, PKN2, as a potential tumor suppressor in colon cancer, can inhibit tumor growth by inhibiting the polarization of tumor‐associated macrophages to M2‐like phenotype." (PMID 33090721, 2020). "In the present study, we found that PKN2 expression in colon cancer cells inhibited tumor growth by inhibiting TAM polarization to M2 like phenotype." (PMID 29368606, 2018). "PKN2 expression was higher in the early stage of colon cancer (AJCC Cancer Staging Manual, 7th edition)." (PMID 29368606, 2018). "The phosphatase activity assays showed that PKN2 increased the activity of DUSP6 in colon cancer cell lines." (PMID 29368606, 2018). "First, we examined the expression of PKN2 using a colon cancer tissue array containing colon cancer tissues from 90 patients." (PMID 29368606, 2018).
colon cancer (continued). "Co-immunoprecipitation(Co-IP) assay showed that DUSP6 directly interacted with PKN2 in colon cancer cell lines." (PMID 29368606, 2018). "Subsequently, a subcutaneous xenograft model of PKN2 transduced colon cancer cells in BALB/c nude mice was constructed." (PMID 29368606, 2018). "Significantly decreased IL4 and IL10 levels were found in PKN2 overexpression colon cancer cells, while profoundly increased IL4 and IL10 expression was detected in PKN2-depleted cells." (PMID 29368606, 2018). "Furthermore, the ubiquitination of HIF‐1α was detected in colon cancer cells transfected with low and high doses of PKN2 plasmid." (PMID 40515512, 2025). "The role of protein kinase N2 (PKN2) in colon cancer is rarely studied." (PMID 40515512, 2025). "We focused on the direct effect of PKN2 on key factors related to angiogenesis in colon cancer." (PMID 40515512, 2025). "There was an inverse association between PKN2 and CD31 expression in colon cancer tissues." (PMID 40515512, 2025). "The expression of PKN2 was examined across various human colon cancer cell lines." (PMID 40515512, 2025). "PKN2 expression was higher in the early stage of colon cancer." (PMID 40515512, 2025). "We further explored the effect of PKN2 on HIF‐1α in colon cancer cells under hypoxic conditions." (PMID 40515512, 2025). "We hypothesized that PKN2 modulates angiogenesis by influencing the paracrine effect of colon cancer cells." (PMID 40515512, 2025). "Additionally, we investigated the levels of secreted VEGFA and bFGF in the culture supernatant of PKN2‐overexpressing, PKN2‐knockdown, and control colon cancer cells." (PMID 40515512, 2025). "Considering the antiangiogenic role of PKN2 demonstrated in our study, enhancing the expression or activity of PKN2 may represent a promising therapeutic strategy for colon cancer." (PMID 40515512, 2025). "Additionally, PKN2 inhibited angiogenesis induced by colon cancer cells in vitro under hypoxic and normoxic conditions." (PMID 40515512, 2025). "Notably, overexpressed PKN2 from colon cancer cells significantly reduced tube formation by EA.hy926 cells under both normoxic and hypoxic conditions (lane one vs. three, lane two vs. four)." (PMID 40515512, 2025). "In this study, we investigated the effect of PKN2 on angiogenesis in colon cancer." (PMID 40515512, 2025). "We hypothesized that PKN2 might suppress M2 polarization via altering the expression profiles of inflammatory cytokines of colon cancer cells." (PMID 29368606, 2018). "Colon cancer cells stably overexpressing wild-type PKN2 or shRNA-PKN2 were generated." (PMID 29368606, 2018). "PKN2 expression in human colon cancer tissues was examined with immunohistochemistry (IHC)." (PMID 29368606, 2018). "Moreover, macrophages cocultured with low level PKN2 cancer cells promoted, while macrophages polarized by high level PKN2 cancer cells inhibited colon cancer cells proliferation by arresting the cell cycle and increasing apoptosis." (PMID 29368606, 2018). "However, the role of PKN2 in colon cancer remains poorly investigated." (PMID 40515512, 2025). "However, our study suggests that PKN2 exerts a tumor suppressor effect in colon cancer." (PMID 40515512, 2025). "PKN2 plays a role in colon cancer, but its function in esophageal cancer (EC) remains unclear." (PMID 40069590, 2025). "This study further explored whether PKN2 inhibits colon cancer growth through alternative pathways." (PMID 40515512, 2025). "However, the functional role of PKN2 in regulating tumor associated macrophages (TAMs) polarization in colon cancer has never been reported." (PMID 29368606, 2018). "We next evaluated how colon cancer specific PKN2 expression may promote M1 polarization in vitro." (PMID 29368606, 2018). "Additionally, PKN2 affected the differentiation of macrophages in human colon cancer tissue." (PMID 29368606, 2018). "Targeting PKN2 signaling pathway may provide a potential therapeutic strategy for colon cancer." (PMID 29368606, 2018).
colon cancer (continued). "We evaluated the correlation between PKN2 expression and microvessel density (MVD) in tumor tissue of patients with colon cancer." (PMID 40515512, 2025). "We demonstrated that PKN2 promotes the ubiquitination and degradation of HIF‐1α in colon cancer cells via direct binding to HIF‐1α." (PMID 40515512, 2025). "Western blot analysis showed that hypoxia promotes the stability of HIF‐1α, while overexpression of PKN2 significantly downregulated the expression and nuclear internalization of HIF‐1α in colon cancer cells." (PMID 40515512, 2025). "Our study showed that PKN2 inhibited the expression and secretion of VEGFA and bFGF by colon cancer cells." (PMID 40515512, 2025). "The correlation between PKN2 expression with both CD31 expression and MVD was investigated in a cohort of 90 colon cancer tissue samples." (PMID 40515512, 2025). "Mechanistically, PKN2 suppresses the expression of IL4 and IL10 from colon cancer cells by inhibiting Erk1/2 phosphorylation, which is required for phosphorylation and binding of CREB and Elk-1 to the promoters of IL4 and IL10." (PMID 29368606, 2018). "There was a significantly positive relation between PKN2 and DUSP6 expression in human colon cancer tissues." (PMID 29368606, 2018). "Additionally, PKN2 directly interacted with HIF‐1α at the protein level and induced phosphorylation, resulting in ubiquitination‐dependent degradation of HIF‐1α in colon cancer cells." (PMID 40515512, 2025). "Moreover, PKN2 inhibited the expression and secretion of VEGFA and bFGF by colon cancer cells by inhibiting the binding of HIF‐1α to the VEGFA and bFGF promoter regions." (PMID 40515512, 2025). "We found that the overexpression of PKN2-WT and PKN2-K686R did not affect colon cancer proliferation in vitro." (PMID 29368606, 2018).
colorectal cancer (5 papers, 2013 to 2025). A primary or metastatic malignant neoplasm that affects the colon or rectum. "Moreover, the expression of PKN2 in colorectal cancer cells has been associated with a favorable prognosis." (PMID 40069590, 2025). "In the context of tumor immunomodulation, PKN2 has been observed to inhibit the polarization of M2-type TAMs in colorectal cancer cells." (PMID 40069590, 2025). "In colorectal cancer, miR‐452‐5p promoted tumor progression by targeting PKN2 and DUSP6 to activate the ERK/MAPK signaling pathway." (PMID 37014625, 2023). "We then investigated the effects of PKN1 and PKN2 siRNAs on WNT3A-dependent AXIN2 expression in osteosarcoma (U2OS), and colorectal carcinoma (RKO) cell lines." (PMID 24114839, 2013).
prostate carcinoma (5 papers, 2011 to 2025). A carcinoma that arises from epithelial cells of the prostate gland. "PKN2 has been shown to contribute to motility pathways in prostate cancer cells and to facilitate gastric cancer metastasis." (PMID 40515512, 2025). "In human prostate cancer cells, PKN2 contributes to motility pathways and influences differentiation during prostate cancer progression." (PMID 29368606, 2018). "The results show that unlike the situation reported in prostate cancer cells, PKN1 and PKN2 can contribute both to cell migration in wound healing assays as well as 3D invasion of tumour cells in transwells." (PMID 21754995, 2011).
breast carcinoma (4 papers, 2017 to 2023). "It was confirmed by western blotting analysis of PKN2 proteins in breast cancer cell lines tested in this study." (PMID 28515445, 2017). "It is notable that PKN2 is one of the highest expressed PKC isoforms in breast cancer cell lines, implicating the importance in tumorigenesis." (PMID 28515445, 2017). "In addition, PKN2 demonstrated a tumor suppressor profile in breast cancer." (PMID 34745257, 2021). "The roles of PDPK1, PKN2, PPP2R2A, and PPP2R5E in PI3K pathway regulation of HER2+ breast cancer progression and inhibition by PGB-0-ol remain unclear." (PMID 38028209, 2023).
bladder cancer (3 papers, 2015 to 2022). "We previously reported a non-redundant role for PKN2 in bladder cancer cell migration, perhaps shedding light on PKN2 isoform specificity." (PMID 26774483, 2016).
heart failure (3 papers, 2022 to 2026). Inability of the heart to pump blood at an adequate rate to meet tissue metabolic requirements. "To determine if variations in PKN2 expression may be associated with human heart failure, we mined an RNASeq database of patients with dilated cardiomyopathy (n = 97) vs normal controls (n = 108)." (PMID 35730579, 2022). "Data from surviving SM22α-Cre+/− Pkn2fl/fl mice (above) suggest the cardiac defect is most likely the result of developmental cardiac abnormalities, however defects in lung development resulting from loss of Pkn2 in smooth muscle cells would impact cardiac function and also lead to heart failure." (PMID 35730579, 2022). "Activating PKN2 may lead to cardiac dysfunction and heart failure, induce pulmonary fibrosis impair actin cytoskeleton assembly and alterecell adhesion." (PMID 40515512, 2025).
adenoma (2 papers, 2018 to 2025). A neoplasm arising from the epithelium. "PKN2 expression was higher in normal colon tissue than in polyps, adenomas, and metastatic adenocarcinomas, decreasing gradually in these conditions." (PMID 40515512, 2025). "Higher expression of PKN2 was found in normal colon tissue compared with polyp, adenoma and metastatic adenocarcinoma." (PMID 29368606, 2018). "We also explored PKN2 expression in normal colon, polyp, adenoma and metastatic adenocarcinoma." (PMID 29368606, 2018). "The expression of PKN2 decreased gradually in polyp, adenoma and metastatic adenocarcinoma." (PMID 29368606, 2018).
bladder tumor (2 papers, 2011 to 2019). "Of these cell lines, we selected 5637 bladder tumour cells as a model for the enriched expression of PKN2." (PMID 21754995, 2011). "Here we employ a cell model, the 5637 bladder tumour cell line where PKN2 is relatively highly expressed, to assess the potential redundancy of these isoforms in migratory responses." (PMID 21754995, 2011). "(2011) where only siRNA anti‐PKN1 or anti‐PKN2, but not anti‐PKN3, had an effect on wound healing closure of 5637 bladder tumor cells." (PMID 30422386, 2019).